EGFR (epidermal growth factor receptor)
Diseases named in the same sentence as EGFR in open-access papers (continued):
Sharing a sentence is not in itself a finding about the gene and the disease.
melanoma (continued). "As another example of paracrine signaling between CAFs and tumor cells, the hepatocyte growth factor (HGF) is secreted by the stroma upon treatment with BRAF or EGFR inhibitors, conferring resistance to melanoma and NSCLC cells, respectively." (PMID 33291749, 2020). "STAT3 is a critical point of convergence downstream of several hyperactive tyrosine kinase receptors that are either mutated or amplified in melanoma, such as KIT, ERBB4, EPH, FGFR, EGFR and PDGRFA, among others." (PMID 33396645, 2020). "Further experiments indicated that the downregulation of p27 is accountable for Gal-1-driven EGFR induction in drug-resistant melanoma cells." (PMID 32784465, 2020). "EGFR is expressed in epithelial cells and its overexpression is found in cancers of epithelial origin, whereas melanoma cells rarely express EGFR." (PMID 31936151, 2020). "Several studies also indicated that overexpression of EGFR was correlated with poor prognosis of malignant melanoma." (PMID 33171861, 2020). "Positive staining of EGFR was observed only in 13 out of 114 melanoma samples (11.4%), and the staining intensity was predominantly weak to moderate." (PMID 31936151, 2020). "Studies performed with experimental murine melanoma models found that cetuximab, a monoclonal antibody that inhibits EGFR activity, reduces tumor invasion and suppresses metastasis formation." (PMID 31996230, 2020). "These genes were related to EGFR signaling, epithelial cell proliferation, skin development, and angiogenesis, which are fundamental biological processes of melanoma development." (PMID 32413516, 2020). "Addiction to EGFR activation was, however, advantageous to melanoma cells only in the presence of drug since the cessation of trametinib treatment led to a growth factor-independent maintenance of TRA-resistant EGFR-expressing cells." (PMID 31936151, 2020). "At the same time, EGFR expression was significantly correlated with metastatic disease status and therefore suggested as prognostic factor in melanoma." (PMID 32605090, 2020). "We focused our attention on the EGFR gene for NSCLC samples, KRAS, and BRAF genes for mCRC samples, and the BRAF gene for melanoma samples, because target therapy for the mutation of these genes can be prescribed by clinicians." (PMID 32054005, 2020). "We therefore investigated the response of metastatic acral and mucosal melanoma to ICI in regard to MDM2/4 or EGFR amplifications and melanoma type." (PMID 32110946, 2020). "Our results indicate that both directed and spontaneous migrations (2D conditions) of melanoma cells are regulated by the EGFR and MET signalling." (PMID 31638339, 2019). "Here, we focused on the influence of simultaneous treatment of melanoma cells with selected inhibitors of EGFR - gefitinib or lapatinib, and MET - foretinib." (PMID 31649529, 2019). "For this reason, we analysed direct involvement of these receptors in the invasion of melanoma cells inducing EGFR and MET up‐ and down‐regulations in examined cells." (PMID 31638339, 2019). "Altogether, our study demonstrated that long-term vemurafenib exposure in BRAF-mutant melanoma can lead to increased migration that correlates with elevated EGFR expression." (PMID 31514305, 2019). "We found that MITF mRNA expression was considerably (p = 0.075) lower, while EGFR mRNA expression was significantly (p = 0.016) higher in fast migrating melanoma cells." (PMID 31514305, 2019). "This work for the first time shows that invasive abilities of melanoma cells are decreased after application of pairs of EGFR and MET inhibitors." (PMID 31649529, 2019). "We also explored possible changes in the expression of epidermal growth factor receptor (EGFR) and platelet‐derived growth factor receptor beta (PDGFRβ), since these receptors have previously been related to BRAFi resistance in melanomas." (PMID 30582770, 2019). "Recent data reveal that inhibition of EGFR pathway induces cell death in human melanoma and T-ALL cells." (PMID 31096997, 2019).
melanoma (continued). "Since EGFR expression showed positive correlation with Erk activation, we tested the EGFR inhibitor erlotinib in our panel of melanoma cells." (PMID 31514305, 2019). "Another mutation predictive of response to EGFR-inhibiting therapy is BRAF, which is associated with a very poor prognosis particularly in colorectal cancer and melanoma." (PMID 31635038, 2019). "An important distinguishing factor of anoikis resistant acidic melanoma cells was the upregulation of EGFR and AKT pathway." (PMID 31275384, 2019). "We have previously shown that combination of foretinib, an inhibitor of MET (hepatocyte growth factor receptor), with gefitinib or lapatinib, inhibitors of EGFR (epidermal growth factor receptor), has a synergistic cytotoxic effect on melanoma cells." (PMID 31649529, 2019). "The obtained results validate the application of combination therapy directed against EGFR and MET in melanoma cells resistant to treatment with inhibitors of mutated BRAF." (PMID 31877948, 2019). "Epidermal and hepatocyte growth factors can stimulate invasive abilities of melanoma cells, while treatment with combination of their receptors' (EGFR and MET, respectively) inhibitors reduces viability of these cells, as we have previously shown." (PMID 31638339, 2019). "Five of the 9 patients with melanoma had tumors bearing known mutations (4 with BRAF mutations and 1 with EGFR mutation)." (PMID 31439037, 2019). "Of note, our data also revealed that EGFR-high melanoma cells express more PD-L1 than EGFR-low cells." (PMID 31514305, 2019). "In our previous work, we have already demonstrated that dual inhibition of EGFR/MET was able to elicit a synergistic cytotoxic effect in melanoma cell lines, accompanied by a decrease in their invasive abilities." (PMID 31877948, 2019). "We found that in EGFR-high melanoma, there is a significantly (p = 0.029) higher PD-L1 expression than in EGFR-low melanoma cells." (PMID 31514305, 2019). "Foretinib (F, MET inhibitor) and lapatinib (L, EGFR inhibitor) used simultaneously were able to synergistically decrease the viability of melanoma cells, and also significantly diminish the invasive abilities and proteolytic activity of these cells." (PMID 31877948, 2019). "In light of these findings, we also tested the EGFR inhibitor erlotinib in our panel of melanoma cells." (PMID 31514305, 2019). "We noticed that protein level of EGFR correlates with the ability to digest fluorescently labelled gelatin by melanoma cells." (PMID 31638339, 2019). "Our research indicates the importance of personalized treatment of patients with melanoma since we have identified the EGFR and MET as potential therapeutic targets." (PMID 29719603, 2018). "Our data suggest a previously unidentified link between the EGFR and Beclin-1 in melanoma cell line." (PMID 30100990, 2018). "As anticipated, only a small subpopulation of melanoma cells expressed a combination of BRAFi-resistance markers (EGFR, ZEB1...) and an α-signature." (PMID 30429474, 2018). "Further, even in settings like BRAF mutant melanoma and EGFR mutant non-small-cell lung cancer (NSCLC), where effective precision therapies have been established, targeted therapies often yield incomplete and transient responses." (PMID 29700304, 2018). "Downregulated mRNAs were mainly enriched in prostate cancer, transcriptional misregulation in cancer, melanoma, epidermal growth factor receptor (EGFR) tyrosine kinase inhibitor resistance, and microRNAs in cancer." (PMID 30237984, 2018). "Next, we decided to investigate the effect of the tested inhibitors on the expression levels of selected proteins implicated in EGFR and MET signaling pathways in melanoma cell lines using Western blot analysis." (PMID 29719603, 2018). "Recently, genetic studies using comparative genomic FISH have shown amplification of whole chromosome 7 and the 7p11.2 region, including the EGFR gene, in a large number of melanoma cases." (PMID 29492214, 2018).
melanoma (continued). "Similar approaches can be used in different tumor types, including melanoma that express epidermal growth factor receptor (EGFR)." (PMID 30261592, 2018). "Our data also suggest a previously unidentified link between the EGFR and Beclin-1 in melanoma cell line." (PMID 30100990, 2018). "Low MITF expression in melanomas has previously been linked to increased expression of RTKs such as AXL, EGFR, and PDGFRβ, which activate immediate–early signaling, causing resistance to RAF/MEK inhibitors." (PMID 28069687, 2017). "Inhibition of EGFR or Src Tyrosine Kinases were also found to be effective in overcome BRAF inhibitor resistance in melanoma cells." (PMID 29113311, 2017). "As already reported, the pathway activated by the EGF receptor (EGFR) plays a crucial role in resistance of melanoma cells to Vemurafenib." (PMID 29113311, 2017). "Markers tested by NGS mainly provide information relevant for using targeted therapy (breast: HER2 IHC; colon: KRAS; lung: EGFR; and melanoma: BRAF)." (PMID 28371134, 2017). "Studies showed that receptor tyrosine kinases (RTK) such as PDGFRβ, IGF1R, EGFR and c-Met were overexpressed in melanoma cells." (PMID 28708099, 2017). "Another study also showed that EGFR is upregulated in both BRAFi-resistant melanoma cell lines and patient tumours." (PMID 28708099, 2017). "This ligand of the epidermal growth factor receptor has been proposed as a prognostic biomarker for gastric carcinoma, also for melanoma." (PMID 29038767, 2017). "In keeping with published studies, there were frequent mutations of BRAF and NRAS in melanoma; BRAF, EGFR, KRAS, and STK11 in NSCLC; APC, BRAF, KRAS, and PIK3CA in CRC; KIT and PDGFR3A in GIST; and CTNNB1 in other tumours (desmoid fibromatosis)." (PMID 28196074, 2017). "We next confirmed that the over-expressions of EGFR, IGF-1R and CRAF were closely associated with resistance to BRAFi in VemR A375 melanoma cells." (PMID 27448964, 2016). "EGFR levels are higher in BRAF-mutant CRCs than in melanomas, explaining why CRCs exhibit EGFR-mediated resistance more frequently." (PMID 27308562, 2016). "Melanoma also frequently exhibits enhanced activation of receptor tyrosine kinases like epidermal growth factor receptor (EGFR) and MET, as well as BRAF and small G proteins such as Ras." (PMID 26762417, 2016). "In the old situation, in peripheral hospitals, we assumed one single-gene test as clinical standard for both NSCLC (EGFR) and melanoma patients (BRAF)." (PMID 27899957, 2016). "Vemurafenib-resistance induced increases in EGFR signalling have been shown to activate an EGFR-SRC-STAT3 signalling cascade in melanoma, and targeting this pathway using inhibitors of SRC inhibits growth of vemurafenib-resistant xenografts." (PMID 27835901, 2016). "Intriguingly, increased receptor tyrosine kinase (RTK) signaling through for instance IGF-1R, PDGFR, or EGFR is also frequently found in relapsed melanomas, and this can lead to ERK activation via classical pathway activation through RAS and CRAF." (PMID 27200346, 2016). "An early analysis of the expression of growth factors and their receptors in melanomas showed that EGF was overexpressed as compared to melanocytes while EGFR was expressed in both melanomas and melanocytes." (PMID 27102439, 2016). "In favor of this role, treatment with cetuximab, a monoclonal antibody targeting the extracellular domain of EGFR, reduced the invasive ability of melanoma cells." (PMID 27102439, 2016). "EGF has a promising therapeutic value as a targeting ligand for tumours overexpressing EGFR, such as melanoma." (PMID 27788212, 2016). "Several studies have shown that over-expression of EGFR, FGFR3, PDGFRβ, CRAF, and NRAS in melanoma have been associated with BRAFi resistance." (PMID 27448964, 2016). "In particular EGFR inhibitors for EGFR-mutant NSCLC and the mutation-selective RAF and MEK inhibitors for BRAF-mutant melanoma are examples of successfully targeted therapy selection." (PMID 26435479, 2015).
melanoma (continued). "The results indicate that the inhibition of the EGFR/MAPK pathway is at least part of the mechanism by which Rg3 inhibits melanoma cell proliferation." (PMID 25672851, 2015). "In the present study, we found that Rg3 significantly inhibited melanoma cell growth through inhibiting EGFR phosphorylation with FUT4/LeY low expression in vitro and in vivo." (PMID 25672851, 2015). "We suggest that Rg3 deactivation of the EGFR/MAPK pathway through downregulating FUT4/LeY expression performs a key role in the treatment of melanoma." (PMID 25672851, 2015). "Stronger staining for EGFR was observed at pT4 than pT3 stages of human melanoma (n = 10) expressing high levels of Swiprosin-1." (PMID 26079945, 2015). "The clinical significance of EGFR expression was examined in ten surgical specimens of five patients with BRAF-mutant melanomas treated at our Institute with the BRAFi Vemurafenib." (PMID 25742786, 2015). "High levels of EGFR were detected, even before therapy, in tumor cells of one of three melanoma patients unresponsive to BRAFi." (PMID 25742786, 2015). "While carrying out this meta-analysis, we also compared the proteomic data to the results of an shRNA screen for mechanisms of EGFR-based drug resistance in melanoma." (PMID 26029660, 2015). "The EGFR/SFK/STAT3 signaling axis was found to be up-regulated in BRAF-resistant melanoma cell lines and in patients with intrinsic or who developed acquired resistance to Vemurafenib." (PMID 26393652, 2015). "The Notch signaling pathway cross-talks with EGFR/ErbB signaling at the mediator level, e.g. when activated, Notch1 contributes to cell growth and survival via Akt-activation in melanoma." (PMID 25599599, 2015). "Based on previous studies showing upregulation of EGF and EGF receptor (EGFR) in malignant melanoma, the correlation between Swiprosin-1 expression and EGFR signaling was examined." (PMID 26079945, 2015). "Our previous study showed that Rg3-induced EGFR/MAPK pathway deactivation inhibiting melanoma cells proliferation via decreasing FUT4/LeY expression." (PMID 26094873, 2015). "Our data collectively indicate that Swiprosin-1 is upregulated via the EGFR signaling pathway in malignant melanoma." (PMID 26079945, 2015). "To validate the NGS platform we first analyzed seven independent tumor FFPE samples from lung, colon and melanoma with known mutations in BRAF (V600E), KRAS (G12S, G13D), and EGFR (L858R and E746_A750del)." (PMID 26124082, 2015). "Recent data from melanoma further support this important role in BRAF mediated transformation, as MIG-6 dephosphorylation was associated with EGFR activation and resistance to BRAF inhibitors." (PMID 26065894, 2015). "Here, we demonstrated that expression of Swiprosin-1 is regulated by EGFR signaling and closely correlated with that of EGFR in human melanoma tissues." (PMID 26079945, 2015). "Consistent with immunohistochemical results from human melanoma tissues, both EGFR and Swiprosin-1 were upregulated in high-metastatic mouse melanoma B16F10 cells, compared to low-metastatic B16F1 cells." (PMID 26079945, 2015). "EGFR (ErbB1), a member of the ErbB family, is a potentially important factor in the pathogenesis of malignant melanoma." (PMID 26079945, 2015). "In this study we performed the molecular appraisal of BRAF, NRAS, CKIT and EGFR genes altogether in a highly selected cohort of melanoma patients with lung metastases, that had been surgically treated with curative intent." (PMID 26305188, 2015). "It is possible that these two “exceptional responders” had Class II-like melanoma, harboring activated EGFR." (PMID 26084293, 2015). "In another study, an inverse association was observed between MITF, Vemurafenib resistance and EGFR in tumor specimen and in melanoma cell lines." (PMID 26393652, 2015).
melanoma (continued). "Multiple RTKs can be co-expressed in resistant melanoma cells, with expression clusters involving EGFR, ERBB3, AXL and PDGFR being identified leading to multiple resistance drivers that are difficult to target with single drugs." (PMID 26426052, 2015). "PI3K/Akt pathway activation in melanoma can also occur through mutational activation of PI3KCA along with the mutational activation of upstream receptor tyrosine kinases such as c-KIT and EGFR." (PMID 25168062, 2014). "Previous studies in commonly used high-passage BRAF-mutant lines have suggested that CRC cells are much less sensitive to vemurafenib than malignant melanoma cells due to an EGFR-mediated reactivation of ERK signaling." (PMID 25309914, 2014). "Melanoma cell lines can be clustered into three groups by crs(h = 2) top-ranked genes, one with EGFR and RAF1 ranked high exclusively, the other with MAPK1 at top rank, and the third with a mixture of EGFR/RAF1/MAPK1." (PMID 24550933, 2014). "BRAF inhibitor–mediated activation of EGFR/SRC family kinase/STAT3 signaling was shown to mediate resistance in BRAF-mutant melanoma cell lines and was confirmed in patient biopsies." (PMID 24743024, 2014). "The most active compound was the EGFR blocker pelitinib that consistently suppressed cell survival in melanoma cell lines with an IC50 value in the low micromolar range." (PMID 24489649, 2014). "That screen identified the SRY (sex determining region Y)-box 10 (SOX10) gene as a regulator of EGFR expression in four different tested melanoma cell lines." (PMID 25031620, 2014). "EGFR is expressed at low or moderate levels in many melanoma cells and was also detected in A375 and LOX IMVI cells." (PMID 24970815, 2014). "Nevertheless, lapatinib, a reversible inhibitor of EGFR, ERBB2, and other kinases is currently in a clinical trial for advanced melanoma with ERBB4 mutations (NCT01264081)." (PMID 24743024, 2014). "The subgraphs in the melanoma mutation network revealed featured pathways such as the Raf/MEK/ERK pathway and receptor signaling pathways (e.g., EGF/EGFR, FGF, PDGFR-beta signaling pathways)." (PMID 24516372, 2014). "Another mechanism of E2F1-induced invasiveness has been confirmed by the E2F1-epidermal growth factor receptor interaction with E2F1 in melanoma progression." (PMID 24023875, 2013). "In agreement with our previous observations, melanoma cell lines express varying levels of EGFR, c-Met, and IGF-1Rβ." (PMID 23418523, 2013). "Here we describe the regulation of potential novel melanoma candidate genes using an inducible version of the EGFR orthologue Xmrk." (PMID 20663135, 2010). "In the Xiphophorus fish melanoma model, a single oncogenic epidermal growth factor receptor, termed Xiphophorus melanoma receptor kinase (xmrk) is responsible for spontaneously developing melanoma." (PMID 20663135, 2010). "Preclinical studies in a mouse xenotransplantation model of melanoma showed synergistic activity of the EGFR inhibitor erlotinib in combination with bevacizumab resulting in reduced tumor volume." (PMID 24281094, 2010). "GAG-β domains somehow interfere with the G3/EGFR interaction and decrease the antiproliferative effect of G3 in melanoma cells." (PMID 17453002, 2007). "For instance, mutations in the epidermal growth factor receptor (EGFR) have been linked to resistance against tyrosine kinase inhibitors in non-small-cell lung cancer (NSCLC), whereas BRAF mutations have been shown to drive resistance in melanoma treatment." (PMID 41144441, 2025). "First, the proliferation of melanoma cell lines in vitro is sensitive to EGFR kinase blockade." (PMID 40649937, 2025). "In practice, systemic-first strategies are reasonable for asymptomatic, small-volume brain metastases from EGFR/ALK-driven NSCLC or BRAF-mutant melanoma, initiating CNS-active systemic therapy and deferring focal radiotherapy with MRI surveillance every 6–8 weeks." (PMID 41296115, 2025).